BRCA1 (BRCA1 DNA repair associated)
Diseases named in the same sentence as BRCA1 in open-access papers (continued):
Sharing a sentence is not in itself a finding about the gene and the disease.
ovarian carcinoma (continued). "However, on the basis of our analyses, the cumulative risk of ovarian cancer for those at the lowest 1% of the PRS by age 40 years is predicted to be 0.7%, and 20% of BRCA1 mutation carriers are predicted to have a risk of ovarian cancer of less than 1.3% by age 40 years." (PMID 28376175, 2017). "A retrospective analysis of 445 women with germline BRCA1/2 mutations (79% of whom had had breast and/or ovarian cancer) found a non-significant (p = 0.06) reduction in overall survival in those with BRCA1 exon 20 mutations compared to those with mutations in BRCA1 exons 2 or 1119." (PMID 29203787, 2017). "For this reason, it is important that effective mechanisms for disseminating new research findings are adopted because if mutations in BRCA1 or BRCA2 can be identified and at-risk relatives are able to adopt preventive measures, the incidence of ovarian cancer may be reduced." (PMID 26574041, 2017). "However, almost none of the research referred to the detection of BRCA1/2 mutations in the plasma from ovarian cancer patients." (PMID 29254167, 2017). "Similarly, we found that in a BRCA1-deficient background of an ovarian cancer cell line, depleting WRN does not suppress upregulated resection, indicating that WRN is not involved in it (Sidorova, unpublished)." (PMID 29355244, 2017). "Data in the literature for ovarian cancer showed an inverse association between PARP1 and BRCA1 expression, supporting the hypothesis that loss or dysfunction of one crucial DNA repair pathway can be compensated by a “shift toward” and up-regulation of alternate DNA repair mechanisms." (PMID 29029467, 2017). "However, neither the prevalence of deleterious variants in BRCA1/2 in ovarian cancer in Germany nor the reliability of family history as trigger for genetic counselling has ever been evaluated." (PMID 29053726, 2017). "Because women with BRCA1 and BRCA2 mutations are already at high risk of developing breast and ovarian cancers, the combined effects of risk-modifying variants could lead to much larger differences in the absolute risk of developing the disease as compared with the general population." (PMID 28376175, 2017). "In this study, we developed different PRSs for breast and ovarian cancer as well as estrogen receptor (ER)–specific PRS based on reported susceptibility loci from population-based studies and evaluated their associations with risks for BRCA1 and BRCA2 carriers." (PMID 28376175, 2017). "Analysis of BRCA1 promoter methylation may contribute to strategies for the identification of women who may benefit from PARP inhibition or other targeted therapies, as has occurred in BRCA associated ovarian cancer." (PMID 27463681, 2016). "Although some studies evaluated BRCA1/2 mutations in breast and/or ovarian cancer patients in our country, only a few of them have performed the entire gene sequencing, none specifically in ovarian cancer patients." (PMID 27914478, 2016). "Furthermore, the effect of the drug combination was corroborated in an intraperitoneal dissemination xenograft mouse model in which SKOV3 ovarian cancer cells responded with significantly decreased BRCA1 expression, suppressed PI3K/AKT signaling and reduced tumor burden." (PMID 26909613, 2016). "The BRCA1/BRCA2 HWA is based on the premise that pathogenic variants in these genes will be identified more often in individuals with strong personal and/or family histories of breast and/or ovarian cancer, while the identification of benign variants should be independent of cancer history." (PMID 27363726, 2016). "Recent data show that GC rs2298849 may be involved in the risk of ovarian cancer among noncarriers of BRCA1/BRCA2 mutations." (PMID 27642296, 2016). "Furthermore, paclitaxel monotherapy is effective in relapsed ovarian cancer in BRCA1 mutation carriers, although this study did not consider possible restoration of BRCA1 function during the prior therapy." (PMID 27555886, 2016).
ovarian carcinoma (continued). "Interestingly, the three examined ovarian cancer cell models that responded well to combination therapy also exhibited concomitantly diminished BRCA1/2 expression, which is consistent with the previously established synthetic lethal interaction between BRCA deficiency and PARP inhibition." (PMID 26909613, 2016). "Further efforts to decipher the mechanisms underlying the antagonistic relationship between 53BP1 and BRCA1 in DSB signaling should help to clarify the role of BRCA1 in protecting against breast and ovarian cancers, and may lead to improved cancer treatment strategies." (PMID 27446204, 2016). "However, only a fraction of ovarian tumors exhibit BRCA1 or 2 mutations and most ovarian cancer patients are not eligible for olaparib treatment." (PMID 26959114, 2016). "However, in breast and ovarian cancer cells with BRCA1 deficiency, 53BP1 signaling in the S/G2 phases is no longer inhibited, and RIF1 and PTIP translocate to DNA break sites via binding to phosphorylated 53BP1 to protect DNA ends from processing." (PMID 27462418, 2015). "It should be noted that, even in the case of highly penetrant cancer predisposition genes, such as BRCA1 and BRCA2, population-based studies have revealed that about half of all heterozygous mutation carriers with incident cancers lack a family history of breast or ovarian cancer." (PMID 26092435, 2015). "Therefore, there is a possibility that DBC1 may be involved in BRCA1/2-related progression of ovarian carcinomas." (PMID 25823848, 2015). "By analyzing the expression profiles and Gene Ontology functional enrichment, we found that carriers of BRCA1/2 alterations and patients with miRNA deregulation shared a common mechanism, regulation of the DNA repair-related pathways, that affects the prognosis of ovarian cancer patients." (PMID 25537514, 2015). "A substantial percentage of BRCA1/2 positive patients diagnosed after the age of 60 (n = 8/20) is consistent with the previous reports, indicating that the incidence of ovarian cancer in older age does not exclude BRCA germline mutation, especially as far as the BRCA2 gene is concerned." (PMID 25366421, 2015). "Subgroup analysis revealed that this effect was restricted to BRCA1/2 non-carriers (per b allele OR 1.33, 95% CI 1.11–1.59, P = 0.002) and was stronger in those who reported a positive family history of breast and/or ovarian cancer (per b allele OR 1.64, 95% CI 1.20–2.22, P = 0.002)." (PMID 26517870, 2015). "Thus the existing figure for the BRCA1 and BRCA2 mutation carrier frequency in French Canadian women with ovarian cancer may be an underestimate." (PMID 25884701, 2015). "Ratajska and colleagues screened 109 BRCA1/2 negative high-risk breast and/or ovarian cancer patients from North-Eastern Poland for BARD1 germline mutations and identified three different BARD1 variants suspected to be pathogenic (c.1690C>T, p.Gln564X; c.1315- 2A>G; c.1977A>G)." (PMID 26075229, 2015). "We believe the fact that our control cohort is heterogeneous represents strength, because it includes patients considered at high risk for BRCA1/2 mutation and those without any established risk factors for ovarian cancer, reflecting the baseline risk group (general population)." (PMID 26301412, 2015). "In the present study, we show that the use of the Ion Torrent PGM sequencer to sequence the coding exons of BRCA1 and BRCA2 genes substantially improves the detection rates of a wide spectrum of mutations in Polish patients with familial and/or only early onset of breast and/or ovarian cancers." (PMID 25948282, 2015). "Our findings imply that the genetic (such as BRCA1 mutation) and epigenetic mechanisms (such as hypomethylated ETS1 motif, and histone modification H3K9ac and transcription factor ETS1 binding) are jointly involved in the malignant progression of PARP1-related ovarian cancer." (PMID 24448423, 2014).
ovarian carcinoma (continued). "We studied BRCA1/2 -negative breast and/or ovarian cancer families to a) assess the contribution of PALB2 mutations in this series and b) identify clinical, pathological and family history characteristics that might make PALB2 screening more efficient." (PMID 25225577, 2014). "GR levels were not sensitive to the BRCA1 knockdown in primary BRCA1-mutated ovarian cancer cells." (PMID 24629067, 2014). "Indeed, deletions encompassing both genes (BRCA1 and beclin-1) and deletions of only BRCA1 but not beclin-1 were found in breast and ovarian cancers, which is consistent with BRCA1 loss representing the primary driver mutation in these cancers." (PMID 25328887, 2014). "Interestingly, we observed that overexpression of BRCA1 was an effective way to induce an increase in GR levels in SKOV3 cells, primary non-mutated and BRCA1-mutated ovarian cancer cells." (PMID 24629067, 2014). "Our results indicate that BRCA1 may be a potential regulator of GR in ovarian cancer cells." (PMID 24629067, 2014). "Notably, we observed that H3K9ac deletion and/or ETS1 enrichment were effective ways to induce a decrease of PARP1 levels in SKOV3 cells and primary non-mutated and BRCA1-mutated ovarian cancer cells (Fig. 3Ei-Eiv)." (PMID 24448423, 2014). "In 175 probands from a clinic based series of breast and/or ovarian cancer families with no detectable BRCA1/BRCA2 mutations, we have identified two mutations in PALB2: one, c.3113G > A, is known to be deleterious and the other, c.3507_3508delTC (p.H1170Ffs*19), is likely to be deleterious." (PMID 25225577, 2014). "However, there have been few reports about the interactions between BRCA1 and GR in ovarian cancer." (PMID 24629067, 2014). "Indeed, this study actually demonstrated the opposite, a normal-range prevalence of low FMR1 alleles in BRCA1/2 mutation-carrying ovarian cancer patients but a trend towards higher prevalence in ovarian cancer patients who were not BRCA1/2 carriers." (PMID 25036526, 2014). "Breast and ovarian cancers, for example, are associated with many genes, not just BRCA1/2." (PMID 25593598, 2014). "In certain studies conducted in the Netherlands and Italy, it was shown that in breast and/or ovarian cancer patients who tested negative for BRCA1 or BRCA2 small mutations, about 20% carried an LGR in 1 of these 2 genes, but many other studies reported a prevalence of under 10%." (PMID 25176351, 2014). "Therefore, the present study was undertaken to investigate AGTR1 expression from genetic (BRCA1 mutated or not) and epigenetic (BRCA1 promoter methylated or not) aspects in ovarian cancer, and to provide novel insights into the regulatory mechanism of AGTR1." (PMID 24321324, 2013). "Since BRCA1 expression is widespread, the function of BRCA1 in mediating HDR and other DNA repair processes does not by itself explain the predilection of BRCA1-mutation carriers to develop such a limited range of tumor types, mostly breast and ovarian cancers." (PMID 23802008, 2013). "Thus, a study of nearly 700 BRCA1 families indicates that breast and ovarian cancers are by far the most common, while there is a higher than expected risk in several additional hormonally related cancers, including cervical cancer, uterine cancer, and prostate cancers in younger men." (PMID 23802008, 2013). "Likewise, BRCA1 and BRCA2 participate in error-free repair of double-strand DNA breaks by homologous recombination (HR) and inherited mutations in these genes predispose to breast and ovarian cancers." (PMID 24265793, 2013). "In addition, BRCA1 mutation-associated cancer that lost the wild-type BRCA1 allele had a better outcome than ovarian cancer with only wild-type BRCA1 (data not shown)." (PMID 24265793, 2013).
ovarian carcinoma (continued). "Thus, a large-scale MLPA exploration of 1506 German families for pathogenic genomic rearrangements in the BRCA1 gene and of 450 families for gross rearrangements in BRCA2 showed that in high-risk groups for hereditary breast and ovarian cancer, the prevalence of rearrangements was 2.1%." (PMID 23344037, 2013). "Interestingly, we observed that overexpression of BRCA1 was an effective way to induce an increase in AGTR1 levels in primary non-mutated and BRCA1-mutated ovarian cancer cells, although AGTR1 levels were not sensitive to the BRCA1 knockdown." (PMID 24321324, 2013). "Our results indicate that BRCA1 may be a potential regulator of AGTR1 in ovarian cancer cells." (PMID 24321324, 2013). "Therefore, it can be predicted that BRCA1 inactivation-related high levels of EGFR may be involved in promoting ovarian cancer progression." (PMID 24321281, 2013). "However, BRCA1 message and protein are often decreased in sporadic breast and ovarian cancers." (PMID 22347400, 2012). "Thus, we conclude that these variants did not modify risk of breast and/or ovarian cancer in BRCA1 mutation carrier." (PMID 22347400, 2012). "Of the remaining 64 women diagnosed at ages 36 through 50 years, but with no family history of breast or ovarian cancer, 47 women were screened for germline mutations in BRCA1 and BRCA2 genes, and three BRCA1 and one BRCA2 carriers were identified (mutation prevalence, 8.5%)." (PMID 23116406, 2012). "In addition to the hereditary breast and ovarian cancer syndrome caused by germline mutations in BRCA1 and BRCA2, ovarian cancer is also present in the Lynch syndrome that is caused by germline mutations in DNA mismatch repair genes and characterized by susceptibility to colorectal cancer." (PMID 23176254, 2012). "Moreover, BRCA1 mutation(s) carrier females have about 15 fold greater risk for developing ovarian cancer when compared to their non-carrier female counterparts." (PMID 22685544, 2012). "Although this hypothesis may not work with tumor tissues where FST expression is high when compared to its normal expression such as in rodent liver tumors, but BRCA1 may offer a tumor suppressive function in the tumors with high activin expression such as human ovarian cancer." (PMID 22685544, 2012). "The chromatograms of BRCA1 gene from affected patients after mutational screening of the exons in all the samples of our study group revealed no pathogenic sequence variant correlating with breast or ovarian cancer pathogenesis." (PMID 21559243, 2011). "The DNA of 40 healthy Slovenian women aged between 50 and 69 years without any personal and familial breast and/or ovarian cancer history was also tested for the presence of all known mutations, UVs and polymorphisms in BRCA1 and BRCA2 genes in Slovenian population." (PMID 21232165, 2011). "An additional 184 women diagnosed before the age of 40 years who had a strong family history of breast or ovarian cancer and who were not known to carry a germline BRCA1 mutation were selected from among women who had been recruited into the BCFR from clinical genetics services." (PMID 21281505, 2011). "Indeed, in 620.5 years of follow-up in the enhanced data set of 72 women with BRCA1/2 mutations (censored at date of oophorectomy in 13 women), no ovarian cancers have occurred." (PMID 20234365, 2010). "Interestingly for ovarian cancer, it has been shown to interact with the BRCA1/BARD1 complex." (PMID 20386695, 2010). "Thus, other regulators of BRCA1 expression may be more important than promoter methylation in ovarian carcinomas for both primary and recurrent neoplasms." (PMID 19602291, 2009). "Finally, the same authors have provided evidence that BRCA1 protein expression may be a predictive marker of chemotherapy response in sporadic epithelial ovarian cancer." (PMID 19825178, 2009).
ovarian carcinoma (continued). "In summary, the 3'UTR polymorphism in PHB appears not to be associated with ovarian cancer risk in women carrying of one of the three Polish BRCA1 founder mutations even when accounting for environmental influences that are considered important in disease risk determination." (PMID 18397521, 2008). "Consequently, large genomic rearrangements in BRCA1 and BRCA2 might still be at least partly responsible for the hereditary predisposition to breast and ovarian cancer in Finland." (PMID 18501021, 2008). "Thus, although we could not formally test efficacy with mortality as outcome, it is unlikely that annual gynaecological screening will reduce mortality of ovarian cancer in BRCA1/2 carriers." (PMID 17426707, 2007). "Expression of BRCA1 might be an important biomarker for cisplatin resistance in ovarian carcinoma." (PMID 19690636, 2007). "However, this does not explain why BRCA1 or BRCA2 mutations predispose so specifically to breast and ovarian cancer nor why BRCA1 or BRCA2 insufficiency can have profound effects on processes such as proliferation and differentiation." (PMID 16538216, 2006). "These families had previously tested negative for mutations in known ovarian cancer predisposition genes, including BRCA1 and BRCA2, and thus the underlying genetic predisposition in these families is currently unknown." (PMID 15918899, 2005). "Although this data set is small, if confirmed, this may be a link in the evidence that the differences in ovarian cancer survival reported, are not due to the type of BRCA1 mutation, but may be secondary to genetic factors shared." (PMID 16229746, 2005). "However, although noncarriers do not have a BRCA1/2 mutation that predisposes them to breast/ovarian cancer at a younger than expected age, they are still at population risk." (PMID 15505627, 2004). "Targeted sequencing allows the simultaneous analysis of multiple genes, with the addition of BRCA1/2 to MGPT for diagnosis of hereditary breast and ovarian cancers." (PMID 41214301, 2026). "We included 1347 women with a BRCA1/2 GPV who had 82 diagnosed cancers (other than breast and ovarian cancer) in our study." (PMID 40427184, 2025). "The FDA has approved multiple PARP inhibitors for the treatment of metastatic breast and ovarian cancers, yet despite the success of PARP inhibitors in treating BRCA1/2-mutant cancers, drug resistance is a major challenge." (PMID 40543584, 2025). "Inhibition of VEGFR3 preferentially affects CD133+ OCSCs, leading to the downregulation of BRCA1 and BRCA2, and thereby restoring chemosensitivity in previously resistant ovarian cancer cell lines." (PMID 41373619, 2025). "BRCA1 and BRCA2 gene frequencies in breast and ovarian cancer patients in other East-Asian populations have been continuously researched on which had led to the discovery of potential founder mutations." (PMID 40531958, 2025). "In cases of ovarian cancer complications, even BRCA2 exhibit sufficiently high odds ratio of 3.06, but BRCA1 stood out with an odds ratio of 19.33, indicating a notably high probability." (PMID 40323562, 2025).